EZH2 (enhancer of zeste 2 polycomb repressive complex 2 subunit)
Diseases named in the same sentence as EZH2 in open-access papers (continued):
Sharing a sentence is not in itself a finding about the gene and the disease.
glioblastoma (continued). "In glioblastomas with increased EZH2 expression, a prolonged depletion of EZH2 leads to a change in cell survival, suggesting that it is worthwhile to investigate the efficacy of treating tumors with EZH2 inhibitors." (PMID 36142368, 2022). "The results indicate that EZH2 is crucial in inducing H3K27 trimethylation via NF-κB in glioblastoma cells." (PMID 36263173, 2022). "Firstly, we estimated five small molecule EZH2 inhibitors for their efficacy in restricting the growth of WT and p65 KO glioblastoma cells using the previously established inhibitor IC50 values." (PMID 36263173, 2022). "To this end, we analysed the 794 p65-controlled genes whose expression is also regulated by EZH2 (708 upregulated and 88 downregulated genes), and the results showed that these genes considerably regulate glioblastoma proliferation and migration." (PMID 36263173, 2022). "Together, our findings suggest that NF-κB promotes glioblastoma proliferation and migration via EZH2 dependent and independent pathways." (PMID 36263173, 2022). "In glioblastoma, for instance, EZH2 interacts with and post-translationally methylates the tumor-promoting inflammatory transcription factor STAT3, thus increasing its transcriptional activity." (PMID 35884510, 2022). "To identify the exact NF-κB pathway affecting the regulation of EZH2 in glioblastoma, we used siRNAs to knockdown individual NF-κB family members and investigated EZH2 protein expression in LN229 and U251 cells." (PMID 36263173, 2022). "Down-regulation of tumor-suppressor miRNAs results in EZH2 activation and subsequent induction of angiogenesis and growth of glioblastoma cells." (PMID 35236381, 2022). "Initial investigations have shown that the mRNA level of EZH2 or p65 is higher in glioblastoma tissues than in normal tissues and relative to poor survival in glioblastoma patients, which we confirmed in GEPIA and CGGA database." (PMID 36263173, 2022). "We performed GO analysis of the differential genes, and the results suggested that both p65 and EZH2 regulate the malignant progression of glioblastoma cells by affecting their proliferation, apoptosis, cell cycle, and migration." (PMID 36263173, 2022). "Significantly, co-activation of NF-κB and EZH2 confers the poorest clinic outcome and glioblastoma can be molecularly stratified by NF-κB and EZH2." (PMID 36263173, 2022). "Here, we found that NF-κB activation specifically dictates H3K27 methylation via upregulating transcription of EZH2 which is also critical for promoting glioblastoma malignant progression, thus revealing the crosstalk between inflammation and epigenetics." (PMID 36263173, 2022). "The results suggested that the NF-κB canonical signalling is the primary pathway to regulate EZH2 expression in glioblastoma." (PMID 36263173, 2022). "In agreement, the correlation coefficient(r) between EZH2 and p65 expression is also the highest amongst NF-κB subunits in glioblastoma tissues from the CGGA database." (PMID 36263173, 2022). "MiRNA-137 can bind to 3′-UTR of EZH2 to diminish its expression, impairing glioblastoma proliferation and angiogenesis." (PMID 35236381, 2022). "Both NF-κB and EZH2 contribute to the malignant progression of glioblastoma 14, 35, and we have demonstrated that the two oncogenes display functional interactions in glioblastoma." (PMID 36263173, 2022). "Here, we discover that chronic inflammation governs H3K27me3 reprogramming in glioblastoma through the canonical NF-κB pathway to target EZH2." (PMID 36263173, 2022). "EZH2 has also been described to facilitate metabolic reprogramming in glioblastomas with a substantial increase in glycolytic metabolism." (PMID 35888776, 2022). "To identify the roles of NF-κB and EZH2 in glioblastoma gene expression, we compared the RNA-seq results of the p65 and EZH2 KO glioblastoma cells with their respective WT control cells." (PMID 36263173, 2022).
glioblastoma (continued). "To test this conjecture, we first used CRISPR/Cas9 to genetically delete EZH2 and p65 in glioblastoma cells." (PMID 36263173, 2022). "Together, these data demonstrated that NF-κB inhibitor CAPE synergises with the EZH2 inhibitor EPZ-6438 to suppress the development of glioblastoma both in vitro and in vivo." (PMID 36263173, 2022). "In adult and pediatric brain tumors, EZH2 expression also increases with tumor grade and it is known to sustain self‐renewal in the cancer stem‐like cell population of glioblastoma." (PMID 32920979, 2021). "An EZH2 deregulation found by DNA methylation-based footprinting analysis showed EZH2 as a potential therapeutic target in glioblastoma." (PMID 33568205, 2021). "Studies have demonstrated that c-MYC downregulation was capable of abolishing tumorigenicity exhibited by EZH2-depleted glioblastoma CSCs." (PMID 34745848, 2021). "In glioblastoma cells, EZH2 inhibition promotes the release of soluble factors capable of shifting human M-DM and murine microglial cells toward an M1 antitumor phenotype." (PMID 33922336, 2021). "LncRNA-NEAT1 has been revealed to be modulated by the epidermal growth factor receptor (EGFR) pathway, leading to glioblastoma multiform progression by the WNT/β-Catenin Pathway by Scaffolding enhancer of zeste homolog 2 (EZH2)." (PMID 33750353, 2021). "For example, EZH2 inhibition enhanced the effect of Temozolomide (TMZ) in TMZ-resistant glioblastoma cell lines." (PMID 34638497, 2021). "This confirms previous data showing that EZH2 silencing in glioblastoma cells reduces oxygen consumption rates." (PMID 33803922, 2021). "In glioblastoma multiforme, EZH2 binds to STAT3 enhancing STAT3 activity by increased tyrosine phosphorylation of STAT344." (PMID 34376807, 2021). "It has been reported that lncRNA NEAT1 binds to the histone methyltransferase EZH2 and subsequently inhibits the expression of the downstream target genes in glioblastoma." (PMID 33901015, 2021). "Collectively, our findings indicate that E2F7 promotes cell proliferation, cell metastasis and tumorigenesis via EZH2-mediated PTEN/AKT/mTOR pathway in glioblastoma." (PMID 32814835, 2020). "In summary, the EGFR/NEAT1/EZH2/β-catenin axis plays a crucial role in the development of glioblastoma." (PMID 32283739, 2020). "Here, we are targeting PI3K signaling pathways in glioblastoma along with EZH2, a known transcriptional regulator." (PMID 33473259, 2020). "NIMA-related kinase (NEK2) was recently shown to phosphorylate EZH2, which protects EZH2 from ubiquitin-dependent proteasome degradation, thereby promoting glioblastoma growth and radio-resistance." (PMID 32873321, 2020). "We also demonstrated, for the first time, that E2F7 is involved in PTEN/AKT/mTOR pathway through regulating EZH2 in glioblastoma." (PMID 32814835, 2020). "The tumour suppressor PTEN is a well-known target of EZH2, which is down-regulated in glioblastoma and correlated with poor overall survival of glioblastoma patients." (PMID 32814835, 2020). "In glioblastoma, siRNA-mediated EZH2 knockdown resulted in fatty acid synthase decrease, accompanied by diminished fatty acid levels." (PMID 32723346, 2020). "The newly identified E2F7/EZH2/PTEN axis is a promising target for clinical intervention of glioblastoma." (PMID 32814835, 2020). "To evaluate the correlation of E2F7 and EZH2 expression in glioblastoma specimens, we analysed the data from TCGA." (PMID 32814835, 2020). "According to the TCGA and French datasets, EZH2 was up-regulated in glioblastoma, and high expression of EZH2 was correlated with poor patient prognosis." (PMID 32814835, 2020). "One study on glioblastoma showed that Nek2 protects EZH2 from ubiquitination-dependent protein degradation and its expression was found to be increased in recurrent tumors." (PMID 31319849, 2019).
glioblastoma (continued). "Ezh2 has been experimentally validated as a direct target of miR-137 in mouse neural stem cells, and also in human glioblastoma cells and neuroblastoma cells by luciferase reporter gene analysis." (PMID 31736707, 2019). "In glioblastoma, EZH2 promotes the expression of ABC transporter MDR, MRP and BCRP to strengthen chemoresistance." (PMID 29556394, 2018). "In order to test if H19 can bind to EZH2 in glioblastoma cells, we performed RNA immunoprecipitation (RIP) experiments in LN229 cells transfected with a vector encoding a myc-tagged EZH2, (or EGFP as control)." (PMID 29643989, 2018). "Michael Platten’s lab identified that AXL, a novel target gene in glioblastoma, is positively regulated by EZH2 and mediates invasiveness driven by EZH2." (PMID 29642503, 2018). "The correlation of Ezh2/Axl/TGF-β in glioblastoma migration/invasion has been researched in our previous study." (PMID 29642503, 2018). "For example, small-molecule inhibition of EZH2 in glioblastoma and DIPG reduced tumourigenesis in vivo, whereas loss of EZH2 in medulloblastoma attenuated growth and promoted differentiation in vitro." (PMID 29759978, 2018). "Recent data have shown that inhibition of EZH2 promotes chemotherapeutic drug temozolomide (TMZ) chemosensitivity in glioblastoma cells." (PMID 29221202, 2017). "EZH2 in glioblastoma leads to cell cycle arrest at the G0/G1 phase, further leading to the uncontrolled cell cycle progression in glioblastoma cells." (PMID 28642877, 2017). "c-Myc and EZH2 interact in glioblastoma CSCs, and c-Myc overexpression rescues the inhibitory effect of 3-deazaneplanocin A, an EZH2 inhibitor, on targeted glioblastoma CSCs." (PMID 28914785, 2017). "Another report also indicated that silencing EZH2 sensitizes glioblastoma cells to chemotherapeutic drug, TMZ, leading to significant induction of apoptosis and G1/S phase arrest in vitro." (PMID 28561778, 2017). "For instance, the lncRNA HOTAIR promotes glioblastoma cell cycle progression in an EZH2 dependent manner." (PMID 29088865, 2017). "To further confirm the role of EZH2 in the glioblastoma metabolic switch in vivo, we used liquid chromatography-mass spectrometry (LC-MS) to examine the effect of EZH2 upregulation on levels of glycolytic metabolites." (PMID 27259264, 2016). "It has been shown that EZH2 methylates STAT3 in glioblastoma stem-like cells which is required for the activation of STAT3-dependent activation of stem cell-associated transcriptional factors and efficient tumorsphere formation." (PMID 27764181, 2016). "In this study, we demonstrated that EZH2, a multifaceted oncogenic protein involved in tumor proliferation, invasion and metastasis, promotes glioblastoma tumorigenesis and malignant progression through activation of the Warburg effect." (PMID 27259264, 2016). "To test that idea, we first assessed EZH2 expression in 105 specimens of glioblastoma tissue and 12 samples of normal human brain tissue." (PMID 27259264, 2016). "IHC analysis showed that EZH2 was up-regulated in 81 (77%) of the glioblastoma specimens as compared to 2 (17%) of the normal brain tissue samples (P < 0.01)." (PMID 27259264, 2016). "HOTAIR promotes glioblastoma cell cycle progression in an EZH2 dependent manner, while its reduction induced colony formation suppression, cell cycle G0/G1 arrest, and orthotopic tumor growth inhibition." (PMID 26252651, 2015). "Such a distinction between early and late response to Ezh2 inhibition was recently reported in a model of glioblastoma in which prolonged knockdown of Ezh2 results in the emergence of “escaper” tumors characterized by an aggressive phenotype." (PMID 26637281, 2015). "In tongue cancer and glioblastoma, EZH2 depletion suppressed tumor growth by arresting cell cycle progression." (PMID 26378043, 2015). "Immunohistochemical detection showed that tumor cells and CAF expressed EZH2 in the nucleus, similar to previous reports in glioblastoma, non-Hodgkin lymphoma, and nasopharyngeal carcinoma." (PMID 25025074, 2014).
glioblastoma (continued). "EZH2-dependent epigenetic silencing of the BMP receptor 1B (BMPR1B) in a subset of glioblastoma tumour-initiating cells (TICs) has also been noted, thereby limiting the extent to which the TICs can respond to differentiation signals." (PMID 22771539, 2013). "One possible glioblastoma-related tumorigenic mechanism involves activation of STAT3 via direct methylation by phosphorylated EZH2." (PMID 24367637, 2013). "Pharmacologic and shRNA-mediated depletion of EZH2 in glioblastoma cancer stem cells reduced their ability to form new spheres in vitro and new tumors in vivo." (PMID 24202337, 2013). "Here we identify a novel target gene in glioblastoma that is positively regulated by EZH2 and mediates invasiveness driven by EZH2." (PMID 23077658, 2012). "We found the expression of EZH2 mRNA to be increased in HBMVECs after co-culture with human U87 glioblastoma cells." (PMID 21297974, 2011). "qRT-PCR revealed that EZH2 expression levels were up-regulated in glioblastoma blood vessels as compared to normal brain vessels." (PMID 21297974, 2011). "To study the anti-angiogenic effect elicited by EZH2 inhibition in vivo, we used a subcutaneous glioblastoma mouse model and the EZH2 inhibitor DZNep." (PMID 21297974, 2011). "In glioblastoma, EZH2 inhibits differentiation, and activates cancer-, cell cycle- and cellular movement-related genes." (PMID 20920292, 2010). "Understanding PMT regulation more broadly may aid in identifying treatments that preferentially target specific subtypes, as demonstrated for CDK4/6 or EZH2 inhibition for proneural glioblastomas and DGKα or BMI-1 inhibition for mesenchymal glioblastomas." (PMID 38337036, 2024). "Upon methylation of STAT3 via EZH2 in glioblastoma stem-like cells, STAT3 activity was enhanced." (PMID 38183103, 2024). "Furthermore, in glioblastoma (GBM), the nuclear expression levels of lysine methyltransferases, such as SETDB1, KMT5B, Suv-39h1, and EZH2, are elevated and associated with advanced histological cancer grades." (PMID 39620228, 2024). "In summary, our research illustrates that PRMT6 acts as an epigenetic regulator, suppressing TRAF6 transcription through histone arginine methylation (H3R2me2a) to inhibit the ubiquitination and degradation of EZH2, thereby promoting invasion and migration of glioblastoma cells." (PMID 39043634, 2024). "Moreover, E2F7 acts upstream of EZH2 as a transcriptional activator in glioblastoma by binding to its promoter." (PMID 38183103, 2024). "In agreement with the presence of the methyltransferase EZH2 in CEGBCs possessing glioblastoma-like traits obtained following chronic infection of HAs with HCMV, we observed the interaction of cellular lncRNA HOX antisense intergenic RNA (HOTAIR) transcripts with EZH2 using RNA CLIP assay." (PMID 38553638, 2024). "Additionally, it has been shown that EZH2 can enhance the STAT3 signaling pathway in glioblastoma and oral squamous cell carcinoma." (PMID 39120328, 2024). "To determine whether PRMT6 regulates EZH2 protein stability, we measured the abundance of EZH2 in PRMT6-depleted glioblastoma cells and control cells treated with CHX." (PMID 39043634, 2024). "Furthermore, a recent study identified the expression of E2F7 activating the transcription of enhancer of zeste homolog 2 (EZH2), thus inducing mTOR signalling in glioblastoma progression." (PMID 39348343, 2024). "Consequently, NKG2D ligands, containing MICA/B and ULBP, are down-regulated by EZH2-92aa in glioblastoma, which accounts for immune escape of glioblastoma to NK cells in clinical treatment." (PMID 38933287, 2023). "This interaction may contribute to the recruitment of EZH2 to specific genomic loci, influencing the epigenetic landscape and gene expression in glioblastoma." (PMID 38003512, 2023). "Moreover, we assessed the impact of TMZ, the antiviral drug GCV, and EZH2 inhibitor (GSK 343) in vitro within this glioblastoma model." (PMID 37147437, 2023).
glioblastoma (continued). "The results of earlier studies also reported that melatonin may act as a tumor inhibitor molecule in glioblastoma stem-like cells by recruiting the EZH2-related axis, which could involve multiple pathways including EZH2‐NOTCH1 and AKT‐EZH2‐STAT3 signaling." (PMID 36759799, 2023). "The lncRNA PRADX peroxiredoxin 1 (PRADX) promotes the nuclear factor-κB (NF-κB) activity via the UBX domain protein 1 (UBXN1) suppression, inducing the tumorigenesis of glioblastoma and colon adenocarcinoma by interacting with the enhancer of zeste homolog 2 (EZH2)." (PMID 35954243, 2022). "To confirm manipulating H3K27me3 status could affect glioblastoma cells, we knocked down the expression of KMKD6A/B (demethylase) and EZH2 (methyltransferase) and then detected the proliferation of glioblastoma cells." (PMID 36263173, 2022). "EZH2 can also methylate STAT3 to increase STAT3 activity in glioblastoma stem cells." (PMID 36612203, 2022). "Our results thus far identified that the development of glioblastoma is regulated by NF-κB through EZH2-dependent and independent pathway and led us to hypothesize that targeting of NF-κB can enhance the anti-cancer effects of EZH2 inhibition in glioblastoma." (PMID 36263173, 2022). "On the other hand, experimental studies have suggested that EZH2 may inhibit pediatric glioblastomas." (PMID 36142368, 2022). "To further identify histone enzymes involved in the methylation of H3K27, we screened a number of methyltransferases and demethylases in glioblastoma cells and identified EZH2 as the principal methyltransferase specifically responsible for H3K27 trimethylation." (PMID 36263173, 2022). "It was found that ectopic overexpression of both p65 and EZH2 could rescue the deletion of p65 in p65 KO cells, suggesting NF-κB targets EZH2 to promote glioblastoma cell proliferation and migration." (PMID 36263173, 2022). "The inhibition of EZH2 reverses TMZ chemosensitivity in glioblastoma." (PMID 35216113, 2022). "Next, we pursued the EZH2-independent NF-κB-regulated glioblastoma oncogenic pathways." (PMID 36263173, 2022). "The proliferation of glioblastoma cells could be blocked by downregulating EZH2 or BMI1 expression, further highlighting the role of both proteins in cancer development." (PMID 33804165, 2021). "Furthermore, EZH2 was extremely secreted in multidrug-resistant human glioblastoma cells U251/TMZ as well as U87/TMZ." (PMID 34745848, 2021). "HOTAIR promotes glioblastoma cell cycle progression in an EZH2-dependent manner." (PMID 34405017, 2021). "Inhibition of EZH2 led to down-regulation of nestin in glioblastoma." (PMID 32903755, 2020). "EZH2 overexpression has been observed in different malignancies, including glioblastoma." (PMID 32634135, 2020). "in pediatric glioblastomas have lower overall amounts of H3K27me3 due to inhibition of the enzymatic activity of PRC2 through interaction with the EZH2 subunit, an epigenetic dysregulation that may promote gliomagenesis." (PMID 33322354, 2020). "In addition, we explored the mechanistic role of E2F7−EZH2 axis in AKT/mTOR activation, and the results suggested that E2F7 promoted glioblastoma progression via EZH2-mediated PTEN/AKT pathway." (PMID 32814835, 2020). "In addition, the knockdown of E2F7 significantly inhibited the binding of E2F7 with EZH2 promoter in glioblastoma cells." (PMID 32814835, 2020). "EZH2 is able to methylate STAT3 to enhance its activity in glioblastoma stem cells." (PMID 29930752, 2018). "Indeed, we showed that H19 binds EZH2 in glioblastoma cells, and that EZH2 binding to NKD1 and other promoters is impaired by H19 silencing." (PMID 29643989, 2018). "EZH2 expression is necessary for the self-renewal of glioblastoma stem cells." (PMID 28384648, 2017). "EZH2 in glioblastoma leads to cell cycle arrest at the G0/G1 phase." (PMID 28642877, 2017). "Further, EZH2 promoted tumorigenicity of glioblastoma stem-like cells by methylating STAT3." (PMID 28410242, 2017).